STAT3 (signal transducer and activator of transcription 3)
Diseases named in the same sentence as STAT3 in open-access papers (continued):
Sharing a sentence is not in itself a finding about the gene and the disease.
lung carcinoma (continued). "Dihydroisotanshinone I could inhibit tumor migration and cell motility, block macrophage recruitment by lung cancer cells, reduce CCL2 secretion, and suppress p-STAT3 signaling in NSCLC A549 and H460 cells." (PMID 36986550, 2023). "Our studies also suggested the inhibition of IL-6/JAK2/STAT3 signal transduction by the exogenous rhTβ4 maybe part of reason for its inhibitory effect on IPF and lung cancer." (PMID 36835236, 2023). "This happens through MAMPs, which then activate the critical downstream signaling pathways, like STAT3 and NF-kB pathways, as well as the ERK and PI3K pathways—regulating cell proliferation, survival, and differentiation—which are upregulated in lung cancer patients." (PMID 37894302, 2023). "In lung cancer, it participates in macrophage function control and facilitates the release of proinflammatory chemokines throughout its target colony stimulating factor 1 (CDF1); it can also inhibit STAT3 and AKT signaling." (PMID 38146340, 2023). "In lung cancer cells, OGT also regulates metastasis ability via activating IL-6/STAT3 signaling." (PMID 37838167, 2023). "In lung cancer 27, TSLNC8 overexpression led to smaller tumor volume and weight, reduced expression of EGFR, p-EGFR, and p-STAT3 levels, and combination with osimertinib administration effectively suppressed tumor growth, enhancing osimertinib's anti-tumor effects." (PMID 37781073, 2023). "In lung cancer, AKR1B1 is a STAT3 activator that promotes glutathione de novo synthesis, eliminates ROS, protects cell from death, and reduces EGFR TKI drug sensitivity by upregulating the cystine transporter SLC7A11, it would be a therapeutic target for dealing with EGFR TKI resistance." (PMID 36512456, 2023). "The findings suggested that GYP might exert anticancer effects in lung cancer and enhance the effects of chemotherapeutic agent cisplatin through the MAPK14/STAT3 signaling pathway." (PMID 36532716, 2022). "Interestingly, there have been reports showing that STIP1 can support the growth and spread of lung cancer and melanoma through the JAK2/STAT3 pathway, a finding in accordance with our current preclinical data." (PMID 35269562, 2022). "Although STAT inhibitors, alone or in combination with other drugs, have achieved promising effects, no STAT3 inhibitor has been approved for the treatment of lung cancer, likely due to their low bioavailability and off-target toxicities." (PMID 36559280, 2022). "Besides JAK2/STAT3 signaling, we also demonstrate that SH2B3 interacts with SHP2 to inhibit the SHP2/Grb2/PI3K/AKT signaling pathway in lung cancer cells." (PMID 35589677, 2022). "Using the same STAT3 conditional deletion in the T-cell lineage, they demonstrated that STAT3-/- CD8+ T cells had increased IFNγ production and increased CXCR3 expression in subcutaneous melanoma (B16) and lung carcinoma (3LL) models." (PMID 35270020, 2022). "In fact, lung cancer has become an interesting model to elucidate the mechanism of action of NT157 since, in this model, signaling mediated by IGF1R-IRS1/2, STAT3, and AXL has already been reported as relevant to the development, progression, and therapeutic response of this type of cancer." (PMID 36224313, 2022). "The AMPK-STAT3 axis has been delineated earlier, albeit not in lung cancer, but in regulating monocyte to macrophage differentiation by alleviating STAT3 phosphorylation." (PMID 35928273, 2022). "The combinational efficacy of YHO-1701 was abolished by BCL-XL overexpression, demonstrating that BCL-XL influences STAT3-mediated adaptive survival and that its downregulation is necessary for inducing apoptosis in adaptive ALK-rearranged lung cancer cells and eradicating residual tumors." (PMID 35228642, 2022).
lung carcinoma (continued). "The activation of TrkB could enhance the activity of STAT3 and its downstream PI3K/AKT signaling pathway, which eventually promote lung cancer cells proliferation." (PMID 36417428, 2022). "The aim was also extended to gain insight into whether simultaneous inhibition of STAT3 activation and FUT4 fucosylation via ALT and Brv-A have any impact on functional role of lncRNA MALAT1 in A549/T lung cancer cells." (PMID 35281907, 2022). "Alternatively, STAT3 can also be targeted by ASO, AZD9150 that decreased the expression of STAT3 and conferred promising antitumor effects in several preclinical cancer models of lymphoma and lung cancer." (PMID 35189921, 2022). "SH2B3 inhibits JAK2/STAT3 and PI3K/AKT signaling pathways to induce anoikis in lung cancer." (PMID 36230714, 2022). "After establishing the expected role of MALAT1, STAT3, and FUT4 in resistant and non-resistant lung cancer cells, we further studied the association of MALAT1 with STAT3 and FUT4 expression in A549/T cells." (PMID 35281907, 2022). "“Direct STAT3 inhibition” may be more effective for suppressing treatment-induced STAT3 activation and the subsequent adaptive survival of ALK-rearranged lung cancer cells." (PMID 35228642, 2022). "The anti-lung cancer activity of curcumin has been reported and curcumin could suppress cell proliferation and induce apoptosis via modulating the JAK2/STAT3 signaling pathway, PI3K/Akt signaling pathway, and Wnt/β-catenin pathway." (PMID 35630767, 2022). "Western blot analysis indeed revealed that Daidzein and Gefitinib combination treatment synergistically inhibited multiple EGFR phosphorylation sites (P-EGFR Y1068, T845 and T1092) in both A549 and H1975 lung cancer cells, which led to deactivation of STAT1 and STAT3." (PMID 35813479, 2022). "Similarly, in A549 human lung cancer cell lines, Curcumin downregulated NF-κB activity and acted on the JAK2/STAT3 signaling pathway by suppressing JAK2 activity; thus, Curcumin is a successful therapeutic drug for treating lung cancer." (PMID 36359936, 2022). "Culturing A549 or CL1-5 lung cancer cells with bone marrow mesenchymal stem cells (MSCs) can increase spheroid formation, drug resistance and overexpression of pluripotent markers by activating IL-6/JAK2/STAT3 pathway." (PMID 36591515, 2022). "STAT3 activity was restored and stably maintained upon initial ALK-TKIs (alectinib, ceritinib, lorlatinib, and brigatinib) treatment in the absence of ALK signaling, characterizing the treatment-induced adaptive survival of ALK-rearranged lung cancer cells." (PMID 35228642, 2022). "Furthermore, these two natural SLs suppressed MALAT1 expression, STAT3 activation, and FUT4 and P-GP expression which are the hallmarks for paclitaxel resistance in A549 lung cancer cells." (PMID 35281907, 2022). "A study on the natural compound polyphyllin I pointed out that the regulation of IL‐6/STAT3 signalling EGFR‐TKI may reverse epithelial‐to‐mesenchymal transition and serve as a potential new way to overcome the EGFR‐TKI resistance in lung cancer." (PMID 35605028, 2022). "However, JAK/STAT3 and PI3K-AKT signaling pathways are responsible for IFNγ-induced PD-L1 induction and immune escape in lung cancer." (PMID 34445462, 2021). "Accordingly, inhibition of STAT3 by niclosamide reverses acquired radio-resistance of NSCLC cancer xenografts and improves tumor shrinkage, while shRNA-mediated knock-down of STAT3 restores sensitivity of lung cancer cells to ionizing radiation." (PMID 34944848, 2021). "Particularly, circHIPK3 also functions as a negative autophagy regulator in lung cancer through the miR124-3p-STAT3-PRKAA pathway which is dependent on STK11 status." (PMID 33634138, 2021). "Blocking the JAK2/STAT3 signaling pathway in non-small cell carcinoma (NSCLC) inhibits the proliferation, angiogenesis, invasion, and migration ability of NSCLC and additionally inhibits the development of lung cancer." (PMID 34900727, 2021).
lung carcinoma (continued). "Therefore, curcumin is a potent suppressor of CSCs in lung cancer and for this purpose, it can inhibit JAK2/STAT3 axis to impair CSC features." (PMID 34769099, 2021). "The lung cancer stemness and CSC features can be mediated via JAK2/STAT3 axis." (PMID 34769099, 2021). "In this regard, we have demonstrated that through promoting the ubiquitination and proteasomal degradation of nuclear STAT3 and RelA, the PDZ-LIM domain–containing protein PDLIM2 functions as a tumor suppressor particularly important for lung cancer suppression." (PMID 33539325, 2021). "Here, we tested the hypothesis that activation of STAT3 is the signaling pathway, downstream of the AGT/Ang II-mediated activation of the AT1-R, that fuels the transformed phenotype of lung cancer cells." (PMID 33380422, 2021). "LncRNAs regulate the sensitivity of lung cancer cells to EGFR‐TKIs chiefly through one of the following mechanisms: 1) MAPK/ERK signaling pathway, 2) PI3K/AKT/mTOR signaling pathway, 3) STAT3 signaling pathway, 4) mitochondrial pathway, 5) cell cycle progression, or 6) EMT." (PMID 33931980, 2021). "On drug resistance, crizotinib inhibited cytoplasmic STAT3, led to EIF2A phosphorylation, then inhibited nuclear STAT3, and then downregulated B-cell lymphoma gene-2 (BCL-2), and finally led to a high level of protective autophagy in lung cancer cells." (PMID 34976824, 2021). "Similar results were observed in another lung carcinoma cell line H358, suggesting that PRMT5 might potentiate STAT3 activation induced by autocrine IL‐6 in lung carcinoma cells." (PMID 34026434, 2021). "In this study, we revealed that ZQT played an immunomodulatory role in an orthotopic lung cancer mouse model via reducing the population of G-MDSCs and inhibiting their immunosuppressive activity in TME by activating the STAT3/Bcl-2/caspase-3 signaling pathway." (PMID 33867859, 2021). "Moreover, we identified STAT3 inhibitor, LL1 as a synthetic chemical agent against lung cancer and comfirmed LL1 plus gefitinib combinational treatment strategy for gefitinib resistance." (PMID 34059647, 2021). "The results showed that high-fat diet (HFD)-related obesity could promote the development of urethane-induced lung cancer in C57BL/6J mice, and the leptin-mediated activation of PI3K/Akt/mTOR/STAT3 pathway was involved in the mechanism." (PMID 33708630, 2021). "STAT3 is also a critical transcriptional regulatory target of EGFR, and its activation regulates DNA damage repair, autophagy, apoptosis, proliferation, angiogenesis, migration, invasion, and immune suppression in lung cancer cells." (PMID 33869036, 2021). "Interestingly, conditioned medium from FAS knockdown cells markedly increased STAT3 phosphorylation, suggesting that increased IL6 expression by FAS knockdown is responsible for STAT3 activation in lung cancer cells." (PMID 32963220, 2020). "Moreover, MEK inhibitor induced STAT3 feedback activation, leading to resistance in KRAS mutant lung cancer cells." (PMID 32872659, 2020). "Moreover, the present study demonstrates the in-depth molecular mechanism of anti-STAT3 activity of BLN-A and functional role of STAT3 in BLN-A-induced apoptosis in A549 lung cancer cells." (PMID 32328177, 2020). "Another report indicated that circHIPK3 played an oncogenic role in lung cancer and acted as a pivotal autophagy controller via miR-124-3p/STAT3/PRKAA axis, and its potential of being prognosis biomarker and treatment target for lung cancer was confirmed as well." (PMID 33817257, 2020). "Immunoblot analysis of sorted lung cancer cells from MSC co-cultures revealed activation of ABL kinases as measured by ABL tyrosine (Y245) phosphorylation and phosphorylation of ABL downstream targets STAT3 (Y705) and CrkL (Y207)." (PMID 33119681, 2020).
lung carcinoma (continued). "Since IL6 could promote STAT3 signaling pathway, we further evaluated IL6 expression after knocking down FAS in lung cancer cells." (PMID 32963220, 2020). "Similarly, in the cytoplasm of lung cancer, EP suppressed the growth, invasion and migration and induced apoptosis of NSCLC cells via the HMGB1/RAGE axis and the NF-κB/STAT3 pathway." (PMID 32742812, 2020). "For instance, we found that EIF3F cooperates with STAT3 and exploited this finding to successfully target EIF3F-overexpressing human lung cancer cells with nifuroxazide, an FDA-approved oral anti-diarrheal agent that has been identified as an inhibitor of STAT3." (PMID 31527668, 2020). "In lung cancer cells, PIM1 stimulates STAT3 phosphorylation to suppress apoptosis." (PMID 32545648, 2020). "Interestingly, STAT3, which is up-regulated in several human carcinomas, including head and neck squamous cell carcinoma (HNSCC), breast, ovary, prostate, and lung cancer, is specifically activated by PKCε." (PMID 32429937, 2020). "Moreover, apoptosis inducer, ING5, inhibits EGFR and IL-6 production, inactivates JAK/STAT3 and AKT pathways through inactivation of the Wnt/β-catenin pathway, and eventually prevents metastasis of lung cancer." (PMID 31952344, 2020). "Constitutive PD-L1 expression, known as innate immune resistance, is created by the deletion or silencing of PTEN found in glioblastoma or by a signal transducer and activator of transcription 3 (STAT 3) signalling found in lymphoma and occasionally in lung cancer." (PMID 31914969, 2020). "Previously, we reported that MUC16 is overexpressed in pancreatic, breast and lung cancer and promotes a rapid G2/M checkpoint transition through its interaction with JAK2/STAT3, leading to accelerated proliferation." (PMID 32709695, 2020). "According to our in vitro data, we speculate that BEL is capable of inducing apoptosis in human A549 lung cancer cells by upregulating the levels of caspase-8/3, reducing the level of PARP1, and ultimately, interfering into STAT3/COX-2 pathways." (PMID 33299414, 2020). "Therefore, we studied the molecular mechanism underlying the anti-proliferative properties of KCP10043F by examining its effect on STAT3 in NSCLC cells and the mouse model bearing xenografts of A549 human lung cancer." (PMID 32150979, 2020). "Activated STAT3 is more highly expressed in ALDH+ cells over ALDH- cells, and inhibition of STAT3 by small molecule inhibitor, Stattic, reduced ALDH1A3 expression in lung cancer stem cells." (PMID 31534498, 2019). "To understand whether KLF3 expression is related to EMT and the STAT3 signaling pathway in patients with lung cancer, we conducted an IHC assay to examine the correlation between KLF3, EMT marker, and STAT3 expression in 56 lung cancer specimens." (PMID 31486564, 2019). "Moreover, reduced KLF3 expression was found in lung cancer tissues, and KLF3‐mediated metastasis was shown to be dependent on the STAT3 signaling pathway." (PMID 31486564, 2019). "Then, we hypothesized that LINC81507 can increase CAV1 via sequestering miR-199b-5p, and thereby inhibiting the STAT3 pathway and EMT in lung cancer cells." (PMID 31296840, 2019). "However, in lung cancer, IFN-γ induces PD-L1 expression through the JAK/STAT3 and PI3K-AKT signaling pathways, leading to immune escape." (PMID 30646912, 2019). "Expressions of JAK1,2,、 STAT3 、PD-L1 and ATM were increased in A549CisR and H157CisR cells and could by induced by cisplatin in parental lung cancer cells." (PMID 30961670, 2019). "Because LDOC1 is a regulator of the IL-6/JAK2/STAT3 axis, LDOC1 may play different roles during different stages of lung cancer." (PMID 30634502, 2019). "Interplay has been reported between EGFR, STAT3, and ALK in lung cancers." (PMID 30634502, 2019).
lung carcinoma (continued). "In the contrary, inhibition of PI3k or Stat3 in non-transformed rodent fibroblasts or epithelial cells or certain human lung carcinoma lines with extensive GJIC inhibits communication, while mutational activation of PI3k or Stat3 increases GJIC." (PMID 30717267, 2019). "Furthermore, the results from mechanistic studies, based on the observed selective regulation of lung cancer metastasis upon PLOD3 depletion, identified STAT3 as the binding partner of PLOD3." (PMID 30442941, 2018). "Moreover, BBR blocked doxorubicin (DOX)‐induced activation of signal transducer and activator of transcription 3 (STAT3) and enhanced the cytotoxic effect of DOX in human lung cancer cells." (PMID 28840963, 2018). "STAT3 protein is 1 of 7 cytoplasmic transcription factor family members including STAT1-6, STAT5a, and STAT5b which are aberrantly activated in lung cancer tissues." (PMID 29456509, 2018). "The mechanistic study clearly revealed that PLOD3 knockdown inhibits STAT3 activation, suggesting that inactivation of STAT3 signaling by PLOD3 may serve as an effective therapeutic approach for lung cancer." (PMID 30442941, 2018). "As a result, we found that STAT3 was not significantly altered in the miRNA‐3127‐5p transduced lung cancer cells, and hEGF as an exogenous stimulus, 300 ng/mL for half an hour, there is still no change after hEGF stimulation." (PMID 29726585, 2018). "Although, the results of the meta-analysis of concerning overall survival are not stable, p-STAT3 can still be regarded as a biomarker indicator for poor prognosis in lung cancer patients." (PMID 28797050, 2017). "In vitro studies of EGFR-mutant lung cancer have shown that the expression of PD-L1 is increased in these cancer cells through downstream effectors in the EGFR pathway, such as STAT3 (signal transducer and activator of transcription 3) and ERK1/2 (extracellular signal-regulated kinase 1/2)." (PMID 29296194, 2017). "Besides, STAT3 is persistently activated in GPCR C5a-knockout (KO) mice, a spontaneous lung cancer developing model, and the use of an antibody against LIF leads to STAT3 inactivation in this model." (PMID 29062084, 2017). "To test our hypothesis, we first evaluated STAT3 acetylation status in both lung tumors from Hdac7+/−/K-Ras mice and HDAC7-depleted human lung cancer cell lines." (PMID 29126425, 2017). "Moreover, synergism between IL-6/JAK/STAT3 and TGF-β/Smad signaling, as well as TGF-β and Raf/MAPK, is required to induce EMT in lung carcinomas, suggesting that EMT is orchestrated by several signaling pathways." (PMID 28415568, 2017). "Additionally, the inhibition of IL-6/STAT3 signaling pathway by IL-6 neutralizing antibody or specific inhibitors of JAK2/STAT3 reversed CAF-CM induced EMT and migration of lung cancer cells." (PMID 29100297, 2017). "We further observed that ALDH1A1 positive cells had higher levels of IL-6R, JAK3 and phosphorylated STAT3, suggesting that the lower levels of miR-218 may be responsible for the upregulation of STAT3 signaling in ALDH positive lung cancer cells." (PMID 28830450, 2017). "Collectively, our data show that LSS-11 is a potent naphthalimide-based chemosensitizer that could enhance cell death in paclitaxel-resistant lung cancer cells through the DR5/PARP1 pathway and STAT3/MDR1/MRP1 STAT3 inhibition." (PMID 29072615, 2017). "Indeed, our data also showed that basal level of Stat3 phosphorylation was upregulated in the TKIR lung cancer cells compared to the corresponding TKIS one, suggesting the involvement of Stat3 signaling in the TKI-resistant mechanism." (PMID 27419630, 2016). "The expression of the proteins (p-STAT3, Bcl-2 and Survivin) showed no obvious changes when the phosphorylation of STAT3 was inhibited or IL11Rα were silenced in lung cancer cells." (PMID 27922075, 2016).